AKR1B1 (aldo-keto reductase family 1 member B)
Diseases named in the same sentence as AKR1B1 in open-access papers (continued):
Sharing a sentence is not in itself a finding about the gene and the disease.
tumor (51 papers, 2002 to 2025). "Microarray‐based prognostic analyses revealed that high AKR1B1 expression was associated with favorable OS in tumors with low tumor purity and high stromal or immune infiltration." (PMID 40396420, 2025). "In depth analysis of the different cell types identified within the myeloid lineage revealed that AKR1B1 expression was the highest in tumor associated macrophages (TAMs) that express C1QC (complement protein C1Q) gene." (PMID 40396420, 2025). "When tumors were stratified based on their tumor purity, immune and stromal contents, microarray‐based AKR1B1 expression was associated with good OS in tumors with high stroma and immune fractions and low tumor purity." (PMID 40396420, 2025). "On the other hand, AKR1B1 expression was strongly associated with good OS when the tumor purity was lower (i.e., more stromal content)." (PMID 40396420, 2025). "Therefore, low AKR1B1 levels directly caused tumor progression." (PMID 37185746, 2023). "Therefore, the potential protective role of AKR1B1 could be explained by its detoxifying function, which decreases oxidative stress and tumor mutations." (PMID 35159076, 2022). "We observed that when tumor purity was high (i.e., tumors had low stromal infiltration), and most of the AKR1B1 expression was contributed by the neoplastic epithelial cells, high expression of AKR1B1 indeed was associated with worse prognosis." (PMID 40396420, 2025). "Beyond this classical metabolic function, AKR1B1 has emerged as a significant player in oxidative stress responses, inflammation, and tumor development." (PMID 41154825, 2025). "Compared with control tumors, tumors derived from AKR1B1-silenced cells presented significantly reduced volumes, slower growth rates, and lower tumor masses." (PMID 40750772, 2025). "In summary, EBF1 exerts potent tumor-suppressive effects in GC by targeting both AKR1B1 and TERT, and restoring EBF1 expression represents a promising strategy for targeted therapy." (PMID 40508012, 2025). "Specifically, AKR1B1 upregulation drives drug resistance acquisition in tumor cells, whereas resistance emergence further amplifies AKR1B1 expression." (PMID 40750772, 2025). "Based on analyses of multiple transcriptomic datasets, we showed that AKR1B1 is highly expressed in the tumor stroma, specifically in CAFs and myeloid cells, compared to relatively lower expression in epithelial cells." (PMID 40396420, 2025). "Tumors with a higher stromal AKR1B1 score also showed a significantly higher tumor AKR1B1 score (p < 0.0001)." (PMID 40396420, 2025). "Altogether, these results support that AKR1B1 expression is higher in tumor subgroups with a denser stromal and immune cell content, and it is expressed primarily in the non‐epithelial cells in the CRC TME." (PMID 40396420, 2025). "With statistically significant differences, CTHRC1, CST6, and AKR1B1 were highly expressed in the tumor and lowly expressed in the normal in both paired and unpaired samples of patients with GC (p < 0.05)." (PMID 40978044, 2025). "Conversely, a trend toward improved OS was observed in patients showing tumor AKR1B1 (competitive inhibitor of AKR1B10) expression, although the difference was again not statistically significant." (PMID 40142797, 2025). "Consistent results were observed in cells overexpressing AKR1B1, as enforced expression of this gene augmented the migration ability of tumor cells of HCT116 and BxPC3." (PMID 39406918, 2024). "We assessed bioluminescence emissions of the excised livers and intestines and found that AKR1B1-induced tumor metastasis was almost completely attenuated by KHK knockdown." (PMID 38200154, 2024).
tumor (continued). "Our results showed that blocking glucose-derived fructose production and metabolism through AKR1B1-KO significantly slowed xenograft tumor growth and reduced tumor weights in A549 and U87 cells." (PMID 39406918, 2024). "Simultaneous expression of AKR1B1 was noticed in individual mixed-lineage tumor cells comprised of different histological subtypes of NSCLC underscoring the value of this protein as a candidate target for therapeutic intervention of these tumors." (PMID 39055885, 2024). "On the 4th week after tumor implantation, bioluminescence analyses showed that the tumor metastasis induced by AKR1B1 overexpression was strongly attenuated by KHK-A knockdown." (PMID 38200154, 2024). "Conversely, increased AKR1B1 expression was related to worse prognosis in GC patients with the tumor invasion depth T3-4 (P = 0.021) or TNM stage I-II (P = 0.018)." (PMID 37751590, 2023). "After tumor formation, the AKR1B1 expression level was further increased with disease progression, which was higher than in early-stage GC tissues." (PMID 37751590, 2023). "Contrary to these observations, extrapolation of ccRCC samples through CPTAC (adjoining normal and ccRCC tumours) demonstrated significantly reduced expression of AKR1B1 in normal kidney tissues compared with its primary ccRCC counterparts." (PMID 37174052, 2023). "Loss of AKR1B1 attenuated the progression of GC, which is similarly achieved by overexpression of EBF1, while overexpression of AKR1B1 weakened the tumor suppressor activity of EBF1." (PMID 36397644, 2023). "For instance, AKR1B1 transcription is enhanced by Twist2, a well characterized promoter of epithelial–mesenchymal transition that cooperates with tumor aggressiveness." (PMID 37780210, 2023). "By binding with EBF1, ZNF521 antagonized its transcription repressor function on the expression of AKR1B1, liberating the tumor‐promoting activity of AKR1B1." (PMID 36397644, 2023). "Gene knockdown experiment verified that AKR1B1 is necessary for tumor growth, suggesting that it can serve as a candidate target for tumor therapy of NSCLC patients with mixed-lineage features." (PMID 35962452, 2022). "Collectively, our functional analysis of AKR1B1 showed that AKR1B1 was necessary for tumor growth and elucidated its transcriptomic regulation in NSCLC." (PMID 35962452, 2022). "To further understand the underlying molecular mechanisms of the tumorigenesis of mixed-lineage tumor cells, we focused on functional analysis of AKR1B1." (PMID 35962452, 2022). "This suggests that AKR1B1 can serve as a candidate target for tumor therapy of NSCLC patients with mixed-lineage features." (PMID 35962452, 2022). "Functional analysis verified that AKR1B1 was necessary for tumor growth, suggesting that it can serve as a candidate target for tumor therapy of NSCLC patients with mixed-lineage features." (PMID 35962452, 2022). "Previous studies have found that AKR1B1 plays a major role in tumor progression, and the mechanisms of action of AKR1B1 include participation in EMT and immune regulation." (PMID 36016566, 2022). "Specially AKR1B1 displayed high expression in all four mixed-lineage tumor subtypes in tumor tissues." (PMID 35962452, 2022). "In contrast to these data, a study conducted in 2015 reported that the expression of AKR1B1 in primary HCC tissues diminished in comparison with non‐tumour tissues as its promoter was heavily methylated." (PMID 32633024, 2020). "Later, in 2018, AKR1B1 expression was reported to increase in HCC gradually from 4‐month nodules to 17‐month tumours in rat models of HCC." (PMID 32633024, 2020). "Moreover, our data suggest a potential crucial role for CTHRC1, CST6, and AKR1B1 in the mitochondria process of tumor cells." (PMID 40978044, 2025). "Therefore, we next evaluated prognostic relationships of AKR1B1 based on tumor purity scores generated by the ESTIMATE method." (PMID 40396420, 2025).
tumor (continued). "Furthermore, analysis of pathological samples from clinical HCC patients revealed high AKR1B1 expression in the tumor tissues of drug-resistant patients, whereas AKR1B1 expression was significantly lower in those who achieved partial remission." (PMID 40750772, 2025). "Although this was not experimentally verified in the current study, we speculate that AKR1B1 expression in cDCs may alter the way the TME supports tumor progression." (PMID 40396420, 2025). "Existing literature demonstrates that AKR1B1 has been reported to modulate reactive oxygen species and inflammatory responses, which could affect immune cell recruitment and function in the tumor microenvironment." (PMID 40978044, 2025). "We further investigate the types of cells expressing CTHRC1, CST6, and AKR1B1 in tumor tissues, and the results indicate that CTHRC1, CST6, and AKR1B1 expression exhibits significant variability in GC, especially within key immune cell populations such as CD8 T cells, B cells, and DCs." (PMID 40978044, 2025). "Moreover, immunohistochemical analysis of AKR1B1 expression in tumor stroma from a cohort of Turkish patients revealed that its expression was associated with favorable overall survival, particularly in tumors with higher stromal infiltration." (PMID 40396420, 2025). "Additionally, Lenvatinib-treated tumors presented reduced vascular density, as indicated by Ki-67 staining, indicating pronounced suppression of tumor proliferation in the AKR1B1-silenced group." (PMID 40750772, 2025). "Thereby, it is reasonable to postulate that AKR1B1 may promote metastasis by facilitating the detachment of tumor cells." (PMID 39406918, 2024). "In conclusion, these findings suggested that AKR1B1 may play a crucial role in promoting tumor metastasis through activation of the RhoA-ROCK2 pathway." (PMID 39406918, 2024). "AKR1B1 was shown to induce tumor development by stimulating cell cycle progression in CRC." (PMID 39055885, 2024). "In line with the RNA sequencing data, P4BH, FASN, AKR1B1, and CBG5 proteins, which have a high prognostic risk, were upregulated in tumor tissues, and MYC proteins, which have a low prognostic risk, were downregulated in tumor tissues compared with normal controls." (PMID 39749345, 2024). "As shown in screened eleven oxidative stress-related DEGs, AKR1B1 is necessary for tumor growth and was found to interact with signal transducer and activator of transcription 3 (STAT3), participating in anti-cell death processes and leading to drug resistance." (PMID 39351147, 2024). "Likewise, AKR1B1 knockdown reduced tumor formation in vivo and lung colonization upon vein tail injection in immunocompromised mice." (PMID 37780210, 2023). "Moderate positive staining of AKR1B1 in the primary tumour was also observed." (PMID 37174052, 2023). "AKR1B1 protein levels were prominently correlated in situ with the subcutaneous neoplasm weight." (PMID 37751590, 2023). "The influence of AKR1B1 expression degree was evaluated on the neoplasm growth in mice." (PMID 37751590, 2023). "The single factor analysis of Cox’s proportional risk model proved that differentiation degree, vascular invasion, neural invasion, tumor invasion depth, lymphaden metastasis, and AKR1B1 expression (P < 0.05) are prognosis factors affecting GC patient survival." (PMID 37751590, 2023). "Then, the cluster analysis was performed based on the neoplasm weight and AKR1B1 protein levels." (PMID 37751590, 2023). "The aberrant AKR1B1 expression can potentially affect the biological behavior of tumor cells." (PMID 37751590, 2023). "Furthermore, gene signatures specific to mixed-lineage tumor cells were identified including AKR1B1." (PMID 35962452, 2022). "Interestingly, SPHK1, with known oncogenic characteristics was the only gene upregulated with > 2.0-fold change and tumour suppressors namely AKR1B1 and KMT2C were down regulated in PDAC-CP." (PMID 35854233, 2022).
tumor (continued). "Multiple lines of evidence suggest that tumour progression could be manipulated by AKR1B1 through modulating a complicated network of miRNAs, proteins and pathways." (PMID 32633024, 2020). "It has been proposed that AKR1B1 inhibition by Fidarestat could prevent tumour growth induced by growth factors in CRC." (PMID 32633024, 2020). "Furthermore, 12‐O‐tetradecanoylphorbol‐13‐acetate (TPA), a potent tumour promoter, was shown to indirectly increase the expression of AKR1B1 by augmenting the expression of protein kinase C (PKC) and NFκB." (PMID 32633024, 2020). "Overexpression of AKR1B1 inactivates these drugs and leads to resistance of various tumor cells." (PMID 27540362, 2016). "However, the study also revealed that elevated levels of another transcription factor, zinc finger protein 521 (ZNF521), in tumor tissues could indirectly promote AKR1B1 expression by suppressing EBF1." (PMID 40508012, 2025). "Since we showed that expression of AKR1B1 from tumor stroma was associated with favorable prognosis via IHC, while bulk transcriptomic data suggested the opposite pattern in certain cohorts, we hypothesized that tumor purity may affect clinical outcomes based on AKR1B1 expression." (PMID 40396420, 2025). "Interestingly, AKR1B1 was associated with poor RFS when the tumor purity was higher (i.e., more epithelial rather than stromal content)." (PMID 40396420, 2025). "Notably, as a secreted protein, AKR1B1 appears to mediate resistance transmission, suggesting that resistant cells may promote tumor heterogeneity by conferring resistance to previously drug-sensitive cells." (PMID 40750772, 2025). "In addition, AKR1B1 inhibition may play the role of an auxiliary therapy rendering tumor cells more sensitive to anti-tumor therapy or alleviating the untoward reactions." (PMID 37751590, 2023). "However, the metastatic RCC tumour showed strong positive staining for AKR1B1." (PMID 37174052, 2023). "Therefore, we focused on the expression changes of AKR1B1 during the occurrence and progression of GC, its relevance with clinical survival and prognosis, and the impact of its aberrant expression on the hyperplasia and metastasis of tumor cells." (PMID 37751590, 2023). "Therefore, we speculated that AKR1B1 may be one of the master regulators of mixed-lineage tumor cells' plasticity." (PMID 35962452, 2022). "Moreover, there is more evidence supporting that lower AKR1B1 could induce resistant of tumour cells to 2DG." (PMID 32633024, 2020). "This broad involvement highlights AKR1B1 as a promising therapeutic target for EMT-driven diseases and for counteracting tumor progression and spread." (PMID 41154825, 2025). "In AML, tumor expressions of AKR1B10, which degrades idarubicin, and AKR1B1, which inhibits the metabolism of idarubicin are important prognostic factors." (PMID 40142797, 2025). "To further investigate the types of cells expressing CTHRC1, CST6, and AKR1B1 in tumor tissues, we utilized the GEO database datasets EMTAB8107 and GSE167297 to conduct a detailed analysis of CTHRC1, CST6, and AKR1B1 expression in STAD." (PMID 40978044, 2025). "Single-cell transcriptomics and spatial proteomics could provide unprecedented resolution in mapping AKR1B1 expression and activity across different cell populations and tissue microenvironments, clarifying its cell-type-specific contributions to fibrosis and tumor heterogeneity." (PMID 41154825, 2025). "Moreover, AKR1B1 is implicated in prostaglandin metabolism, particularly in the synthesis of PGF2α, which stimulates cell proliferation, while also modulating pro-apoptotic pathways activated by agents such as 15-deoxy-PGJ2, collectively influencing tumor cell survival and proliferation." (PMID 40978044, 2025).
tumor (continued). "More recently, Yang and colleagues demonstrated that AKR1B1 interacts with STAT3 and indirectly support EMT, enhancing tumor cell survival under oxidative stress." (PMID 41154825, 2025). "Strikingly, significance with OS was lost in tumors with high tumor purity, emphasizing the effect of TME content and the cell types expressing AKR1B1 in AKR1B1's prognostic relationships." (PMID 40396420, 2025). "Many tumor suppressors and oncogenes modulated by H2A.J play important roles in the regulation of energy metabolism (IGFBP3; IGFBP4; IGFBP5; AKR1B1; SOD2)." (PMID 39062630, 2024). "Overexpression of AKR1B1 can lead to excessive generation of PGF2α and COX2 resulting in inflammation and tumor development." (PMID 39055885, 2024). "Therefore, we hypothesized that AKR1B1 overexpression may cooperate with tumor progression." (PMID 37780210, 2023). "In the second published study, we examined the ratio of AKR1B1 and AKR1B10 mRNA levels in tumor tissues versus adjacent control tissues in relation to the clinicopathological data of 51 patients." (PMID 34298614, 2021). "This profile of genes includes AGPAT3, AKR1B1, PLD1, and UGT8, all of which have previously been reported to be involved in tumor proliferation." (PMID 34568042, 2021). "In addition to targeting AKR1B1, EBF1 also influences tumor progression by interfering with telomerase activity." (PMID 40508012, 2025). "To validate our computational findings, we performed experimental validation using qRT-PCR, confirming significant overexpression of CTHRC1, CST6, and AKR1B1 in GC tissues compared to adjacent normal tissues (p < 0.05), with HPA data further confirming elevated protein levels in tumor tissues." (PMID 40978044, 2025). "While AKR1B10 expression was significantly higher in HCC tumor tissues relative to normal tissues, AKR1B1 expression was not remarkably different between tumor and normal tissues." (PMID 39055885, 2024). "When KHK-A was silenced, AKR1B1 overexpression failed to promote local tumor expansion and tumor metastasis in diabetic mice." (PMID 38200154, 2024). "Although the expression of AKR1B1 was elevated in primary ccRCC versus normal kidney tissues and positively correlated with the high stages of tumours versus normal tissue, it was not prognostically significant." (PMID 37174052, 2023). "According to GEPIA in a GBM tumor, there is also increased expression of AKR1B1, decreased expression of AKR1C1 and AKR1C2, and no change in AKR1C3 expression." (PMID 36765904, 2023). "Intriguingly, the AKR1B1 expression level did not significantly affect the tumor invasion depth T1-2 (P = 0.050) or patients with TNM stage III (P = 0.618)." (PMID 37751590, 2023). "In addition, epithelial cell differentiation regulation-related genes, such as AKR1B1, SPRR1B, and keratin genes KRT6A, KRT19, and KRT17 were also highly expressed in mixed-lineage tumor cells." (PMID 35962452, 2022). "AKR1B10 and AKR1B1 are closely related to inflammation, and AKR1B10 in particular regulates inflammatory factors in the tumor microenvironment, which mobilizes the host immune response and promotes tumor suppression." (PMID 32615540, 2020). "Nevertheless, AKR1B1 also has a negative side since it can promote tumor chemoresistance and contribute to the perpetuation of inflammation and to the development of secondary diabetic complications." (PMID 27540362, 2016). "Thus, its pharmacological inhibition using AKR1B1 inhibitors may offer a promising strategy to target EMT-related pathways across various diseases and tumor types, underscoring the novel therapeutic potential of AKR1B1." (PMID 41154825, 2025). "Furthermore, slides 13 and 14 show negative staining of the tumor cells for AKR1B1, which competitively inhibits AKR1B10, which explains why the patient remained refractory to treatment." (PMID 40142797, 2025).